CTLA4 (cytotoxic T-lymphocyte associated protein 4)
Diseases named in the same sentence as CTLA4 in open-access papers (continued):
Sharing a sentence is not in itself a finding about the gene and the disease.
metastatic melanoma (continued). "Anti-PD-1 and anti-CTLA-4 have revolutionized the treatment of metastatic melanoma, and checkpoint inhibitors have become a standard of care for those with advanced disease." (PMID 33802954, 2021). "A decrease in circulating tumor DNA (ctDNA) assessed in peripheral blood during ICI therapy has been found to correlate with response to combined anti-CTLA-4 and anti-PD-1 therapy in metastatic melanoma patients." (PMID 34656158, 2021). "PD-1 inhibitors (nivolumab, pembrolizumab) and anti-CTLA-4 (CD152) (ipilimumab) are widely used in metastatic melanoma." (PMID 34638410, 2021). "Given the limitations in CRC-directed immunotherapy, early studies focused on the interaction between the microbiome and anti-PD-1/CTLA-4 therapies in metastatic melanoma." (PMID 34307839, 2021). "It began in 2011 when CTLA-4 (cytotoxic T-lymphocyte-associated protein 4) blocking antibody was approved by the Food and Drug Administration (FDA) for treatment of patients with metastatic melanoma." (PMID 34307177, 2021). "Six metastatic melanoma clinical cohorts treated with immune checkpoint inhibitors [anti-cytotoxic T lymphocyte antigen-4 (CTLA-4) or anti-programmed cell death-1 (PD-1)] were recruited in this study." (PMID 35069558, 2021). "The therapeutic benefit of immune checkpoint blockade of PD-1 and CTLA-4 in the treatment of metastatic melanoma is variable." (PMID 33336264, 2021). "Only 20–30% of patients with metastatic melanoma responds to monotherapy with anti-CTLA-4 or anti-PD-1 antibodies to block immune checkpoints." (PMID 34572847, 2021). "Immune checkpoint blockade (ICB) with anti-PD-1/anti-PD-L1 and anti-CTLA-4 is now a standard option for the clinical management of several cancers, especially metastatic melanoma." (PMID 34789823, 2021). "Virtually all metastatic patients with metastatic melanoma who progress after initial treatment with PD-1 or CTLA-4 directed antibodies will die of their disease." (PMID 34743688, 2021). "This gene is of particular interest because immune check point inhibitors that target CTLA4 in the treatment of metastatic melanoma can lead to the development of myasthenia gravis." (PMID 34279044, 2021). "This phase I/IIa trial explores the potential synergistic effect of CTLA-4 blockade and hTERT vaccination, allowing for unchecked expansion of hTERT-specific T cell clones, in HLA-unselected patients with metastatic malignant melanoma." (PMID 34046035, 2021). "Pitifully, both clinical study and application of anti-CTLA4 antibodies were merely confined to metastatic melanoma." (PMID 34399770, 2021). "The fractal dimensions and the multifractal spectrum of the 18F-FDG tracer dispersion were studied in patients with metastatic melanoma before and after treatment with PD-1 inhibitors as monotherapy or in combination with the CTLA-4 inhibitor ipilimumab." (PMID 34680319, 2021). "In 2010, ipilimumab, an anti–CTLA-4 monoclonal antibody, improved overall survival in patients with previously treated metastatic melanoma." (PMID 35126126, 2021). "A 61-year-old female with metastatic melanoma presented with widespread indurated, waxy skin changes, and weight loss following combined anti-PD1 and anti-CTLA4 immunotherapy." (PMID 33879687, 2021). "Conversely, a recent phase I study evaluating RT in combination with anti-CTLA-4 in metastatic melanoma showed CD8 infiltration to be significantly correlated with PFS (NCT01557114)." (PMID 34733287, 2021). "The results showed that serum IL-8 levels correlate with tumor burden changes in metastatic melanoma following treatments with anti-PD-1 mAbs plus anti-CTLA-4 mAbs." (PMID 35011682, 2021). "The first approved ICI was ipilimumab, an anti-cytotoxic T-lymphocyte-associated protein 4 (CTLA-4), for the treatment of unresectable or metastatic melanoma in 2011." (PMID 34571876, 2021).
metastatic melanoma (continued). "Another immunotherapeutic cohort of advanced/ metastatic melanoma patients (treated with anti-PD-1/ PD-L1 or anti-CTLA-4 agents) was also curated for validating the ICI predictive roles of the immune risk signature." (PMID 34747719, 2021). "It has been shown that combining an anti-CTLA-4 mAb (ipilimumab) with an anti-PD-L1 mAb (nivolumab) can help achieve satisfactory results in metastatic melanoma, metastatic CRC, and advanced renal cell carcinoma." (PMID 34367975, 2021). "Immune checkpoint inhibitors targeting cytotoxic T-lymphocyte associated protein-4 (CTLA-4) and programmed cell death-1 (PD-1) have radically improved survival outcomes for metastatic melanoma patients." (PMID 34771465, 2021). "The most evident clinical response to the CTLA-4 blockade (ipilimumab and tremelimumab) was seen in advanced metastatic melanoma patients." (PMID 34575943, 2021). "This signature was detected in anti-CTLA-4 responsive metastatic melanoma prior to the administration of treatment and correlated with response to therapy." (PMID 34376232, 2021). "The utilization of ipilimumab, which is a CTLA-4 blocker, has demonstrated promising results in fighting against the metastatic tumors especially metastatic melanoma." (PMID 32902664, 2021). "Both the mother and the foetus have been successful in the treatment of metastatic melanoma with anti‐CTLA‐4 and anti PD‐1 therapy." (PMID 34708495, 2021). "PRO-C3 is found to be released by TGF-β stimulated CAFs in vitro, and high PRO-C3 in pre-treatment serum has been shown to predict poor overall survival in metastatic melanoma patients treated with anti-CTLA-4 or anti-PD-1 therapy." (PMID 34656158, 2021). "Nivolumab and Ipilimumab were the first combination of PD-1/CTLA-4, which has shown safety and superior efficacy in metastatic melanoma." (PMID 34391428, 2021). "Over the past decade, the development of ICI therapies with blocking antibodies directed against anti-CTLA-4, anti-PD-1, and anti-PD-L1 has totally changed the fate of metastatic melanoma patients thanks to their impressive therapeutic efficacy." (PMID 33809167, 2021). "We validated our findings using published data from 106 metastatic melanoma patients biopsied prior to treatment with PD1 or sequential PD1/CTLA4 blockade." (PMID 34215730, 2021). "In metastatic melanoma, combined PD-1 + CTLA-4 inhibition has produced 5-year progression free survival rates of 37% with 5-year overall survival exceeding 50%." (PMID 34743688, 2021). "The monoclonal antibody targeting CTLA-4 (ipilimumab) was the pioneer checkpoint inhibitor on the market, achieving a significant improvement in overall survival (OS) in metastatic melanoma patients." (PMID 34281259, 2021). "Of interest, anti-CTLA-4 treatment has been demonstrated to decrease PMN-MDSCs in patients with metastatic melanoma." (PMID 33804050, 2021). "In particular, the treatment of metastatic melanoma with combined anti-programmed cell death protein 1 (anti-PD1) and anti-cytotoxic T-lymphocyte-associated protein 4 (anti-CTLA4) antagonists has resulted in median 5-year survival rates of over 50%." (PMID 33879687, 2021). "In this latter study, a large transcriptomic analysis of peripheral blood CD8+ lymphocytes was performed for metastatic melanoma patients receiving anti-PD-1 or anti-CTLA-4 therapy." (PMID 34360781, 2021). "To illustrate this, we present the case of a 78-year old male treated by anti-CTLA-4/ipilimumab for metastatic melanoma." (PMID 34281259, 2021). "In 2011, the first immune checkpoint drug anti-CTLA4 was approved by the USFDA for the treatment of metastatic melanoma." (PMID 33717106, 2021). "In 2011, ipilimumab, which targets cytotoxic T-lymphocyte-associated protein 4 (CTLA-4), was approved by the U.S. FDA for the treatment of cancer after demonstrating improved overall survival (OS) in patients with metastatic melanoma." (PMID 33924623, 2021).
metastatic melanoma (continued). "recently identified an association between a higher TMB and TERT mutations, conferring an improved prognosis in patients with metastatic melanoma receiving CTLA-4 blockade, and thus, for combined targeting of telomerase and CTLA-4 in these patients." (PMID 34046035, 2021). "Ten years ago, the first immune checkpoint inhibitor targeting CTLA4 was approved by the FDA to treat patients with metastatic melanoma." (PMID 34572799, 2021). "More recently, adjuvant immunotherapy agents targeting cytotoxic T-lymphocyte-associated protein-4 (CTLA-4) and programmed death-1 (PD-1) regulatory pathway have been used successfully as adjuvant immunotherapy agents for metastatic melanoma." (PMID 33777924, 2021). "A SubMap analysis was then conducted to compare the expression profiles of two cervical SCC subtypes with a published metastatic melanoma cohort containing 56 patients that received anti-PD-1 or anti-CTLA-4 treatment." (PMID 34030694, 2021). "In patients treated for metastatic melanoma with a combination of anti–PD-1 and anti–CTLA-4 therapy, ALT increase of any grade and grade ≥3 was observed in 37 and 16% of patients, respectively." (PMID 35126126, 2021). "Data from the Sharma laboratory in both preclinical models as well as patients with bladder cancer, prostate cancer, and metastatic melanoma suggested that increased ICOS protein expression on CD4+ T cells was indicative of a response to CTLA-4 treatment." (PMID 33594075, 2021). "Foxp3 expression was decreased in metastatic melanoma, while CTLA4 expression was significantly increased." (PMID 33669410, 2021). "The FDA’s approval of Ipilimumab, an antibody targeting cytotoxic T lymphocyte-associated antigen-4 (CTLA-4), is considered a milestone in cancer treatment and has led to substantial patient outcomes unresectable or metastatic melanoma." (PMID 34507594, 2021). "In this work, the authors used the antibodies Ipilimumab to activate the CTLA-4 antigen in patients with metastatic melanoma and showed that the use of the drug increased the survival period of the patients." (PMID 35087799, 2021). "Ipilimumab is the first antagonistic CTLA-4 antibody approved by the US Food and Drug Administration in 2011, improving overall survival (OS) in patients with advanced or metastatic melanoma." (PMID 32983126, 2020). "Analysis of peripheral blood of 59 metastatic melanoma patients showed increased levels of MDSCs and their chemoattractant factors in patients poorly responsive or resistant to treatment with the CTLA-4 inhibitor." (PMID 33036192, 2020). "In the phase III CheckMate 067 trial, 945 therapy-naive patients with metastatic melanoma received the anti-PD-1 antibody nivolumab in combination with the anti-CTLA-4 antibody ipilimumab or nivolumab, or ipilimumab as monotherapy." (PMID 31947592, 2020). "The same analysis was performed and results were validated for the Van Allen dataset in the context of metastatic melanoma and anti CTLA-4 therapy using ipilimumab antibody." (PMID 32858956, 2020). "As expected, blockade of CTLA-4 using an anti-CTLA-4 monoclonal antibody (Ipilimumab) correlates with an activation of T-cells in metastatic melanoma patients." (PMID 32344813, 2020). "It was only after 2010, with the introduction of immunotherapy (anti-PD-1, anti-CTLA-4 antibodies), that a breach in the status of an unapproachable disease of metastatic melanoma was achieved." (PMID 32685786, 2020). "In particular, the combination of anti-PD-1 (nivolumab) and anti-CTLA-4 (ipilimumab) has shown positive results in tumor treatment and significant enhancement in patients with metastatic melanoma, advanced RCC, and metastatic CRC." (PMID 32620130, 2020). "Ipilimumab (yervoy), the monoclonal anti-CTLA-4 antibody, was first approved for unresectable and metastatic melanoma in 2011, soon followed by its approval as an adjuvant therapy." (PMID 33256089, 2020).
metastatic melanoma (continued). "A phase I trial was designed to determine the safety and efficacy of bevacizumab in combination with the CTLA-4 inhibitor ipilimumab in metastatic melanoma." (PMID 32983126, 2020). "With the approval of CTLA4 inhibitor Ipilimumab for clinical applications, it has been used for metastatic melanoma after the first-line treatment." (PMID 33117084, 2020). "Our findings show that a biomarker measuring granzyme B degraded type IV collagen (C4G) is predictive for response to anti-CTLA-4 therapy in metastatic melanoma patients." (PMID 32998446, 2020). "CIT with CTLA-4-blocking mAbs is efficient in approximately 20 % of patients with metastatic melanoma, and with PD-1 mAbs in approximately 40 % of patients." (PMID 31903160, 2020). "Immunotherapy with checkpoint inhibitors such as ipilimumab, a cytotoxic T-lymphocyte antigen-4 (CTLA-4) inhibitor, and nivolumab, a programmed death-1 (PD-1) inhibitor, has significantly improved the survival of patients with metastatic melanoma." (PMID 32676241, 2020). "Here, the authors show that short-chain fatty acids, which are generated through bacterial fermentation, increases immune tolerance leading to resistance to anti-CTLA-4 immunotherapy in mice and patients with metastatic melanoma." (PMID 32358520, 2020). "As the first ICPI, ipilimumab, which can block cytotoxic T lymphocyte-associated antigen-4 (CTLA-4), was approved by the US Food and Drug Administration (FDA) for the treatment of metastatic melanoma in 2011." (PMID 32183814, 2020). "Recently, immune checkpoint blockade, particularly using mAbs targeting PD-L1, PD-1, or CTLA-4 has achieved outstanding therapeutic efficacy for patients with metastatic melanoma, NSCLC, microsatellite stable colorectal cancer, and other tumor types." (PMID 32714324, 2020). "Since the CTLA4 inhibitor ipilimumab (the first ICB approved by the FDA) has significantly prolonged the OS of patients with metastatic melanoma, CTLA4 inhibitors have proven to be effective agents for many cancers." (PMID 33117084, 2020). "In particular, IDO inhibitors have been tested in a phase I/II clinical trial in combination with ipilimumab (anti-CTLA4) in patients with metastatic melanoma." (PMID 32375310, 2020). "In 2011, the United States Food and Drug Administration (FDA) approved the first immune checkpoint inhibitor, ipilimumab, a monoclonal antibody targeting cytotoxic T lymphocyte-associated antigen 4 (CTLA-4), for the treatment of metastatic melanoma." (PMID 33488843, 2020). "Recent studies showed that VISTA expression increased after the blockade of PD-1 in metastatic melanoma and of CTLA-4 in prostate cancer,respectively." (PMID 33505908, 2020). "Particularly, ipilimumab—an antibody targeting the CTLA4 antigen, has been shown to significantly improve the survival outcome in patients with metastatic melanoma." (PMID 33076303, 2020). "Nowadays, anti-cytotoxic T-lymphocyte-associated protein 4 (CTLA-4) and anti-programmed death-1 (PD-1) antibodies represent a standard treatment for metastatic melanoma." (PMID 32992737, 2020). "The combination of Nivolumab + Ipilimumab (anti-PD-1 + anti-CTLA-4 antibodies) manages to provide survival rates of over 50% at 5 years for cases of metastatic melanoma." (PMID 32685786, 2020). "Immune checkpoint blockade therapies targeting cytotoxic T-lymphocyte-associated antigen 4 (CTLA-4) or programmed cell death protein 1 (PD1) have shown efficacy in many cancers, like metastatic melanoma and non-small cell lung carcinoma." (PMID 32882873, 2020). "In a Phase I study, combined treatment with anti-VEGFA antibody and anti-CTLA-4 antibody achieved favorable outcomes in patients with metastatic melanoma." (PMID 30811474, 2019). "High response rates of metastatic melanoma have been reported upon immune checkpoint inhibition by PD-1 blockade alone or in combination with CTLA-4 inhibitors." (PMID 31300044, 2019).
metastatic melanoma (continued). "Tremelimumab (CP-675,206; AstraZeneca), another human IgG2 mAb to CTLA-4, has demonstrated some success in Phase I and II clinical trials for metastatic melanoma, but in 2008, it was terminated in Phase III trials due to treatment failure." (PMID 30975211, 2019). "Immune checkpoint inhibitors including anti-CTLA-4 and anti-PD-1/PD-L1 antibodies are yielding impressive responses in intracranial manifestations of metastatic melanoma and NSCLC." (PMID 31803366, 2019). "Single cell profiling of tumor-infiltrating immune cells from 32 metastatic melanoma patients treated with anti-PD-1- and/or CTLA-4 antibodies identified two major CD8+ T cell states associated with clinical outcome." (PMID 31557787, 2019). "The advent of anti-PD-1 antibodies along with antibodies targeting cytotoxic T-lymphocyte-associated protein 4 (CTLA-4) and therapies targeting BRAF mutation has provided multiple options to treat patients with metastatic melanoma." (PMID 31428149, 2019). "While immune checkpoint CTLA4 or PD-1 blockade therapy, monotherapy or combined, achieved significant survival benefits in patients with metastatic melanoma, a highly immunogenic human tumor." (PMID 31446896, 2019). "Due to the high demand for effective systemic therapies for metastatic melanoma and recent advances with PD-1 and CTLA-4 inhibitors, significant work is ongoing to reduce rates of primary and secondary resistance to these drugs." (PMID 35582566, 2019). "Accordingly, combining GM-CSF to the anti-CTLA-4-blocking antibody Ipilimimab increases the efficacy of the latter in patients with metastatic melanoma." (PMID 30769926, 2019). "For example, anti-CTLA-4 antibody treatment enhances tumor immunity in metastatic melanoma patients." (PMID 31253768, 2019). "In a human setting, it has also been shown that anti-CTLA-4 antibody treatment prior to tumor resection is feasible and well-tolerated in patients with metastatic melanoma." (PMID 31398192, 2019). "Ipilimumab is a monoclonal antibody directed against CTLA-4, which is involved in downregulating cytotoxic T-cell production, and is approved for treatment of metastatic melanoma." (PMID 31803366, 2019). "A gender-based obesity paradox was recently demonstrated in the context of immunotherapy (anti-CTLA4/PD-1/PD-L1) and targeted therapy in metastatic melanoma." (PMID 30922394, 2019). "A Phase I trial combining epacadostat and ipilimumab (anti-CTLA-4) was well tolerated in patients of metastatic melanoma." (PMID 30853982, 2019). "In recent years the introduction of target therapies with BRAF and MEK inhibitors (MAPKi) and of immunotherapy with anti-CTLA-4 and anti-PD-1 monoclonal antibodies have dramatically improved survival of metastatic melanoma patients." (PMID 31557826, 2019). "PD-1 and CTLA-4 alone or in combination have been very successful and are approved for the treatment of metastatic melanoma and advanced PD-L1-positive non-small cell lung cancer (NSCLC)." (PMID 31614774, 2019). "Analysis of longitudinal tumor biopsy specimens from metastatic melanoma patients treated with anti-CTLA-4 or anti-PD-1 identified a subset of initial responders whose disease progressed with resistant tumors no longer expressing B2M." (PMID 31703593, 2019). "Although the anti-CTLA-4 antibody improved survival in a minority of metastatic melanoma patients, the vast majority suffered autoimmune-related adverse events (irAEs)." (PMID 31046789, 2019). "Treatment with immunotherapy targeting checkpoint inhibitors PD-1 or CTLA-4 significantly increases survival in patients with metastatic melanoma over other standards of care, with anti-PD-1 and anti-PD-1/CTLA-4 combination therapy emerging as most effective." (PMID 31597568, 2019). "Fecal transplantation studies from metastatic melanoma patients to tumor-bearing, germ-free mice treated with anti-CTLA-4 therapy demonstrated abundance of Bacteroides spp." (PMID 30887236, 2019).